CASP14 (caspase 14)
Description:
Non-apoptotic caspase involved in epidermal differentiation. Is the predominant caspase in epidermal stratum corneum. Seems to play a role in keratinocyte differentiation and is required for cornification. Regulates maturation of the epidermis by proteolytically processing filaggrin (By similarity). In vitro has a preference for the substrate [WY]-X-X-D motif and is active on the synthetic caspase substrate WEHD-ACF. Involved in processing of prosaposin in the epidermis (By similarity). May be involved in retinal pigment epithelium cell barrier function. Involved in DNA degradation in differentiated keratinocytes probably by cleaving DFFA/ICAD leading to liberation of DFFB/CAD.
Synonyms: MICE; MGC119078; MGC119079; caspase-14; ARCI12
Tractability: Small molecule: a drug acting on it is in phase 2 or 3 trials. Antibody: its Gene Ontology location is reachable by antibodies, with medium confidence. PROTAC: a small molecule that binds it is known.
Target class: Cysteine protease C14 family; Cysteine protease; Enzyme; Protease; Cysteine protease C14A subfamily; Cysteine protease CD clan
Gene: Protein-coding gene on chromosome 19 (15,049,480 to 15,058,293, forward strand). Ensembl gene ENSG00000105141.
Subcellular location: Cytoplasm; Nucleus
Subcellular location (Human Protein Atlas): Cytosol; Nucleoplasm; Mitochondria
Pathways (Reactome):
Developmental Biology: Differentiation of Keratinocytes in Interfollicular Epidermis in Mammalian Skin; Formation of the cornified envelope
Gene Ontology:
Molecular function: protein binding; cysteine-type endopeptidase activity; cysteine-type peptidase activity; peptidase activity
Biological process: cornification; epidermis development; keratinization; positive regulation of neuron apoptotic process; proteolysis
Cellular component: cytoplasm; cytosol; nucleoplasm; nucleus; cornified envelope; keratin filament
Genetic constraint (gnomAD): Loss-of-function variants: 27 observed, 30.6 expected, observed/expected ratio (o/e) 0.88, 90% interval 0.65 to 1.22. The upper end of that interval is the gene's LOEUF score, 1.22, which puts it in group 5 of 6, group 1 being the genes least tolerant of losing a copy. Missense variants: 323 observed, 322 expected, observed/expected ratio (o/e) 1, 90% interval 0.92 to 1.1. Synonymous variants: 115 observed, 119.95 expected, observed/expected ratio (o/e) 0.96, 90% interval 0.82 to 1.12.
Homologues: Orthologues: chimpanzee CASP14 (98% identical), macaque CASP14 (94% identical), dog CASP14 (86% identical), rabbit CASP14 (83% identical), pig CASP14 (81% identical), guinea pig CASP14 (74% identical), mouse Casp14 (74% identical), rat Casp14 (71% identical), Caenorhabditis elegans ced-3 (29% identical), Drosophila melanogaster Decay (27% identical), Drosophila melanogaster Dronc (26% identical), zebrafish casp8 (25% identical), and 3 more. Paralogues in human: CASP3 (31% identical), CASP7 (30% identical), CASP6 (29% identical), CASP8 (29% identical), CASP10 (27% identical), CASP2 (27% identical), CASP9 (27% identical), CASP1 (26% identical), CASP12 (23% identical), CASP4 (23% identical), CASP5 (23% identical), CFLAR (18% identical), and 4 more.
Diseases named in the same sentence as CASP14 in open-access papers:
CASP14 is named in the same sentence as 69 diseases in open-access papers, as found by Europe PMC text mining. Sharing a sentence is not in itself a finding about the gene and the disease. The quoted sentences say what the papers report.
atopic dermatitis (5 papers, 2021 to 2025). "Furthermore, caspase-14 expression has been described in various types of cancer and diabetic retinopathy In the context of the skin diseases, increased expression of caspase-14 has been found in cancerous lesions, while decreased expression was associated with psoriasis or atopic dermatitis." (PMID 38824481, 2024). "The expression level of KLK7, a physiological activator of caspase 14, and the enzyme initiating the degradation of filaggrin, is mostly increased in human and murine atopic dermatitis tissues." (PMID 34946332, 2021). "In psoriatic skin and in lesions of atopic dermatitis, caspase-14 is diminished." (PMID 40723785, 2025). "As caspase-14 plays an essential role in the epidermal skin barrier, it has to be involved in the development of skin disease, with the most important symptom being epidermal skin barrier dysfunction, i.e., atopic dermatitis." (PMID 34070382, 2021). "In a mouse model of atopic dermatitis, allergic sensitization is not controlled by caspase-14." (PMID 40723785, 2025). "The expression level of caspase-14, similarly to pyrrolidone carboxylic acids (PCA), which are natural moisturizing factors, is significantly decreased in inflammatory lesions compared to non-lesional areas of the skin affected by atopic dermatitis." (PMID 34070382, 2021).
breast carcinoma (5 papers, 2017 to 2026). "Upregulation of the CASP14 as a novel hypoxia-regulated gene bound by HIF1 has previously been observed in breast cancer and our previous study in HNSCC cell lines has pointed at CASP14 as highly hypoxia-upregulated." (PMID 38016355, 2024). "When we applied heteroDE to breast cancer samples, we identified 7 cfRNA biomarkers (SCGB2A2, CASP14, FABP7, CRABP2, VGLL1, SERPINB5, TFF1), 3 of which (FABP7, SCGB2A2, CASP14) overlap with previously identified DCB genes." (PMID 33883548, 2021). "KLHDC7B, CASP14, and PRSS1 are putatively oncogenic gene that has been demonstrated in breast cancer and pancreatic cancer, and the role of KLHDC7B was correlated with extracellular communication, cell morphology, gene expression, and actin binding." (PMID 33987102, 2021).
psoriasis (5 papers, 2016 to 2024). An autoimmune condition characterized by red, well-delineated plaques with silvery scales that are usually on the extensor surfaces and scalp. "Caspase-14 has been closely associated with the development of skin diseases such as photoaging and psoriasis." (PMID 38790770, 2024). "Likewise, in the flaky skin (fsn/fsn) mouse model of psoriasis, topical epigallocatechin gallate treatment upregulates caspase-14 and ameliorates psoriasis." (PMID 39625520, 2024). "Topical application of Dp (0.5 and 1 mg/cm2 skin area) on psoriasis from lesions present on the flaky skin of mice significantly decreased the lesions and provoked the expression of proteins that are downregulated in psoriasis like caspase-14." (PMID 35369062, 2022). "Our experiments of caspase-14 immunohistochemical staining in mice damaged epidermis confirmed the topical application of EGCG effectively increase the epidermal caspase-14 expression of IMQ-induced psoriasis-like lesions and early intervention had better effects." (PMID 27581210, 2016).
diabetic retinopathy (3 papers, 2012 to 2024). "We recently showed that caspase-14 is a novel molecule in retina with potential role in accelerated vascular cell death during diabetic retinopathy (DR)." (PMID 25121097, 2014). "We also determined caspase-14 expression in the retinas of human subjects with or without diabetic retinopathy (DR) and in experimental diabetic mice." (PMID 22876114, 2012).
gastric cancer (3 papers, 2021 to 2023). A primary or metastatic malignant neoplasm involving the stomach. "As regards localized gastric cancers, caspase-14 immunostaining was significantly lower in poorly differentiated tumors compared to well-differentiated ones." (PMID 34070382, 2021). "Lower caspase-14 expression correlated with shorter overall survival in patients with T3N0M0 stage gastric cancer." (PMID 34070382, 2021).
skin inflammation (3 papers, 2020 to 2024). "The protective effects of PF and PW on UVB-induced skin inflammation and skin barrier damage in human immortalised epidermal keratinocytes (HaCaT) cells (including cell viability, ROS, HO-1, NQO1, IL-1β, IL-8, TNF-α, KLK-7, FLG, AQP3 and Caspase 14 levels) are investigated." (PMID 36771204, 2023).
COVID-19 (2 papers, 2022 to 2024). A disease caused by infection with severe acute respiratory syndrome coronavirus 2. "While CASP-14 specific inhibitors have not been explored, pan-caspase inhibitors may be used in COVID-19." (PMID 38755665, 2024).
diabetes (2 papers, 2012 to 2014). "We also determined the impact of diabetes or high glucose on caspase-14 expression in the retinas of human subjects and mice, as well as cultured retinal microvascular cells." (PMID 22876114, 2012). "We hypothesized that enhanced expression of caspase-14 promotes the accelerated death of microvascular cells during diabetes." (PMID 22876114, 2012). "Hence, altered production of caspase-14 may play a key role in the pathogenesis of retinal microvascular dysfunction during diabetes." (PMID 22876114, 2012). "Our previous study demonstrated that caspase-14 is normally expressed in the retina and various retinal cells including RPE cells and was upregulated in human and mouse retina during diabetes." (PMID 25121097, 2014).
melanoma (2 papers, 2024). A malignant, usually aggressive tumor composed of atypical, neoplastic melanocytes. "On the other hand, the Caspase-14, Caspase-7, and Caspase-2 genes revealed decreased mRNA levels in response to UA treatment in A-375 melanoma cells, although these decreases were statistically insignificant (p < 0.05)." (PMID 39473730, 2024). "In malignant melanoma cells, caspase-14 is activated, and its expression level affects the sensitivity of melanoma to chemotherapeutic agents." (PMID 39329914, 2024).
ovarian carcinoma (2 papers, 2021). A malignant neoplasm originating from the surface ovarian epithelium. "Lower caspase-14 expression was associated with the advanced clinical stage in ovarian cancer and with shorter overall survival among ovarian cancer patients with serous tumors." (PMID 34070382, 2021). "Particularly, we examined if ANPEP (from EC2), CASP14 and CLEC2B (from EC3), CADM3 and NRBP2 (from EC4), and SPC25, ESCO2, and GTSE1 (from EC5) are responsible for ovarian cancer cell proliferation by the cell viability assay." (PMID 34459128, 2021). "Additionally, our study identified a number of novel markers, such as CASP14, CLEC2B, CADM3, NRBP2, SPC25, ESCO2, and GTSE1, which are upregulated in a cluster‐specific manner and critical for ovarian cancer cell proliferation and migration." (PMID 34459128, 2021).
viral infection (2 papers, 2022 to 2024). "Thus, future studies that evaluate additional mutant HSV-1 strains could unmask a possible role for caspase-14 and GSDMA during viral infection." (PMID 36146839, 2022).
alopecia (1 paper, 2010). Hair loss usually from the scalp. "Thus, although it is not clear how HR regulates Casp14expression, both loss of Hr expression and Hr overexpression lead to alopecia through expression of Casp14 expression." (PMID 21083932, 2010).
Alzheimer disease (1 paper, 2025). A progressive, neurodegenerative disease characterized by loss of function and death of nerve cells in several areas of the brain leading to loss of cognitive function such as memory and language. "In addition, CASP14 is involved in pertussis (P = 0.0557), legionellosis (P = 0.0557), Alzheimer’s disease (P = 0.101), and pathways in cancer (P = 0.2499)." (PMID 40029616, 2025).
autosomal recessive congenital ichthyosis 12 (1 paper, 2025). "Human patients with a rare frameshift mutation of CASP14 develop autosomal recessive congenital ichthyosis 12 (ARCI12)." (PMID 40723785, 2025).
cervix carcinoma (1 paper, 2022). "Evidence sheds light on the crucial role of caspase-14 in the skin, with highly differentiated cornified areas of lung squamous cell carcinoma and cervix carcinoma." (PMID 35777300, 2022).
cholesteatoma (1 paper, 2021). A pathologic process characterized by the proliferation of keratinizing squamous epithelium resulting in the accumulation of keratin and cells in the middle ear and/or mastoid. "Caspase-14 protein was detected both in the normal external auditory canal and cholesteatoma, but its expression was shown to be greater in cholesteatoma on Western blot analysis." (PMID 34070382, 2021). "As shown with real-time reverse-transcription PCR, the expression level of caspase-14 mRNA in the cholesteatoma epithelium was significantly higher than in the normal external auditory canal epithelium." (PMID 34070382, 2021).
colitis (1 paper, 2022). Inflammation of the colon. "In contrast, ∆pep27 immunization inhibited DSS-induced caspase-14 expression to attenuate experimental colitis via restoration of functional Tregs and healthy gut microbiota composition, suggesting a robust regenerative and antioxidant mechanism to re-establish immunological tolerance." (PMID 36144473, 2022).
colon cancer (1 paper, 2021). "Contrary to cervical, ovarian, and colon cancers, caspase-14 expression was increased in ductal breast carcinoma in situ and invasive cancers compared to the normal mammary epithelium." (PMID 34070382, 2021). "The expression of caspase-14 was significantly reduced in the tested material from the cervical, ovarian, and colon cancer specimens." (PMID 34070382, 2021).
diabetic macular edema (1 paper, 2014). "Our results suggest that caspase-14 contributes to RPE cell barrier disruption under hyperglycemic conditions and thus plays a role in the development of diabetic macular edema." (PMID 25121097, 2014).
eczema (1 paper, 2025). "It was shown that PCA and caspase-14 levels are decreased in inflammatory AD lesions, manifesting as significant epidermal impairments and clinical severity of eczema." (PMID 41294623, 2025).
escherichia coli infection (1 paper, 2025). Infection with the organism Escherichia Coli. "CASP14 and ABCF2 are involved in the pathogenic Escherichia coli infection (P = 0.0792)." (PMID 40029616, 2025).
glaucoma (1 paper, 2012). Increased pressure in the eyeball due to obstruction of the outflow of aqueous humor. "A recent study demonstrated a marked increase in the amount of caspase-14 present in aqueous humor of patients with glaucoma, supporting the presence of caspase-14 in the eye and its potential role in ocular diseases including DR." (PMID 22876114, 2012).
Hematuria (1 paper, 2021). The presence of blood in the urine. "Remarkably, we also found the expression of exosomal GAS5 was significantly negatively associated with the tumor grade and degrees of hematuria (all P < 0.05), whereas, the exosomal KLHDC7B, CASP14, PRSS1, and MIR205HG showed positive correlation with tumor grade and hematuria degrees." (PMID 33987102, 2021).
Hyperglycemia (1 paper, 2014). An increased concentration of glucose in the blood. "Here, we evaluated whether caspase-14 is implicated in retinal pigment epithelial cells (RPE) dysfunction under hyperglycemia." (PMID 25121097, 2014). "This led us to test the effects of caspase-14 knockdown in RPE cell's hyperglycemia-induced barrier dysfunction." (PMID 25121097, 2014). "However, the current study found that, similar to hyperglycemia, overexpression of caspase-14 leads to hyperpermeability of RPE cells." (PMID 25121097, 2014). "Thus, our data implicate caspase-14 in hyperglycemia mediated RPE barrier dysfunction and apoptosis." (PMID 25121097, 2014). "Here we investigated whether caspase-14 also contributes to hyperglycemia-induced RPE barrier dysfunction, which constitutes the outer retinal barrier." (PMID 25121097, 2014). "To test whether caspase-14 is implicated in hyperglycemia-induced RPE dysfunction, we first evaluated the changes in caspase-14 expression in ARPE-19 cells grown in HG (30 mM D-glucose) or in NG (5 mM D-glucose + 25 mM L-glucose) for 5 days." (PMID 25121097, 2014). "To further evaluate the impact of caspase-14 expression on RPE barrier function we examined the changes in the distribution and expression of ARPE-19 cell cytoskeleton protein F-actin, which is known to increase and become disorganized by hyperglycemia." (PMID 25121097, 2014).
ichthyosis (1 paper, 2025). Disorders of cornification that are characterized by visible scaling and/or hyperkeratosis of most or all of the skin. "Gene knockout in mice, evolutionary gene loss in aquatic mammals and the association of human CASP14 mutations with ichthyosis indicate that caspase-14 is associated with the barrier function of mammalian skin." (PMID 40723785, 2025).
ischaemic stroke (1 paper, 2021). "We detected the specific expression of C1QA and Casp14 in the EVs of patients with CSC ischaemic stroke and the specific expression of ANXA2 in the EVs of patients with SC involvement." (PMID 34356850, 2021).
keloid (1 paper, 2022). An irregularly shaped, elevated mark on the skin caused by deposits of excessive amounts of collagen during wound healing. "CASP14, a protein that is required for the cornification process, was also downregulated in keloids." (PMID 35435317, 2022).
larynx squamous cell carcinoma (1 paper, 2022). "Its upregulation reduced cell viability in cisplatin-resistant tongue and larynx squamous cell carcinoma cell lines by downregulating the genes for aquaporin-3 (AQP3), caspase-14 (CASP-14) and arachidonate 12R-lipoxygenase (ALOX12B)." (PMID 36287119, 2022).
lung adenocarcinoma (1 paper, 2021). A carcinoma that arises from the lung and is characterized by the presence of malignant glandular epithelial cells. "It was shown that lung adenocarcinoma overexpressed caspase-14." (PMID 34070382, 2021). "Lung adenocarcinoma was the target cancer that was also analyzed in correlation with caspase-14." (PMID 34070382, 2021).
nonalcoholic fatty liver disease (1 paper, 2025). "The most significant is that CASP14 and MLXIPL participate in the metabolism of nonalcoholic fatty liver disease (P = 0.0006)." (PMID 40029616, 2025).
osteoarthritis (1 paper, 2018). A noninflammatory degenerative joint disease occurring chiefly in older persons, characterized by degeneration of the articular cartilage, hypertrophy of bone at the margins and changes in the synovial membrane. "Casp 1 and Casp14 were upregulated in both virus and σB treated group which showed the activation of apoptosis that may lead to activation of osteoarthritis." (PMID 29731966, 2018).
Parkinson disease (1 paper, 2024). A progressive degenerative disorder of the central nervous system characterized by loss of dopamine producing neurons in the substantia nigra and the presence of Lewy bodies in the substantia nigra and locus coeruleus. "For example, the abundance of the Caspase 14 protein, encoded by gene CASP14, is increased in the plasma of patients with Parkinson’s disease and could serve as a potential disease biomarker." (PMID 38153694, 2024).
preeclampsia (1 paper, 2009). Preeclampsia is a hypertensive disorder of pregnancy that is characterized by new-onset hypertension with proteinuria presenting after 20 weeks of gestation, and depending on mild or severe forms may initially present with severe headache, visual disturbances, and hyperreflexia. "We contend that inappropriate caspase-14 activity during trophoblast differentiation may be involved in the onset of preeclampsia." (PMID 19747408, 2009).
Psoriasiform dermatitis (1 paper, 2016). A skin abnormality characterized by redness and irritation, with thick, red skin that displays flaky, silver-white patches (scales). "Topical application of EGCG alleviated psoriasiform dermatitis, improved the skin pathological structure by reduce the expression of epidermal PCNA, promoted the expression of caspase-14." (PMID 27581210, 2016).
retinal diseases (1 paper, 2014). "Collectively, our findings indicate caspase-14 as a potential player in retinal diseases associated with RPE barrier dysfunction such as DME." (PMID 25121097, 2014).
salivary gland carcinoma (1 paper, 2021). A carcinoma that arises from the major or minor salivary glands. "It was presented that the exogenous expression of caspase-14 reduced the tumorigenicity of the model cell lines of salivary gland carcinoma." (PMID 34070382, 2021). "Conversely, some malignancies, like salivary gland carcinoma, may be cases in which caspase-14 could be the target molecule for treatment." (PMID 34070382, 2021).